ANKRD6 (ankyrin repeat domain 6)
Description:
Recruits CKI-epsilon to the beta-catenin degradation complex that consists of AXN1 or AXN2 and GSK3-beta and allows efficient phosphorylation of beta-catenin, thereby inhibiting beta-catenin/Tcf signals.
Synonyms: KIAA0957
Tractability: PROTAC: ubiquitination databases record sites on it.
Gene: Protein-coding gene on chromosome 6 (89,433,119 to 89,633,838, forward strand). Ensembl gene ENSG00000135299.
Subcellular location (Human Protein Atlas): Vesicles
Gene Ontology:
Biological process: establishment or maintenance of cell polarity; regulation of Wnt signaling pathway
Cellular component: cytoplasm; nucleus
Genetic constraint (gnomAD): Loss-of-function variants: 50 observed, 72.83 expected, observed/expected ratio (o/e) 0.69, 90% interval 0.55 to 0.87. The upper end of that interval is the gene's LOEUF score, 0.87, which puts it in group 3 of 6, group 1 being the genes least tolerant of losing a copy. Missense variants: 785 observed, 818.73 expected, observed/expected ratio (o/e) 0.96, 90% interval 0.9 to 1.02. Synonymous variants: 314 observed, 318.36 expected, observed/expected ratio (o/e) 0.99, 90% interval 0.9 to 1.08.
Homologues: Orthologues: chimpanzee ANKRD6 (99% identical), macaque ANKRD6 (94% identical), dog ANKRD6 (93% identical), pig ANKRD6 (91% identical), guinea pig ANKRD6 (90% identical), rabbit ANKRD6 (90% identical), mouse Ankrd6 (83% identical), rat Ankrd6 (83% identical), tropical clawed frog ankrd6 (68% identical), zebrafish ankrd6b (51% identical), Drosophila melanogaster dgo (21% identical). Paralogues in human: ANKRD10 (11% identical), NRARP (6% identical).
Diseases named in the same sentence as ANKRD6 in open-access papers:
ANKRD6 is named in the same sentence as 15 diseases in open-access papers, as found by Europe PMC text mining. Sharing a sentence is not in itself a finding about the gene and the disease. The quoted sentences say what the papers report.
colon carcinoma (3 papers, 2021 to 2024). "For instance, the expression of ANKRD6 and ITIH3 was associated with reduced OS in colon carcinoma (COAD) and kidney renal papillary cell carcinoma (KIRP), and the expression of CCDC178 in bladder urothelial carcinoma (BLCA) and thyroid carcinoma (THCA)." (PMID 38480611, 2024).
colorectal cancer (3 papers, 2023 to 2024). A primary or metastatic malignant neoplasm that affects the colon or rectum. "In gliomas, the positive expression of ANKRD6 is associated with advanced tumor grade, whereas in non-small cell lung cancer (NSCLC) and colorectal cancer (CRC) is correlated with poor prognosis, advanced stages and poor differentiation." (PMID 38480611, 2024).
breast carcinoma (2 papers, 2024). "In this sense, ANKRD6 is overexpressed in breast cancer, wherein its high level is associated with advanced TNM stages and nodal invasion." (PMID 38480611, 2024).
melanoma (2 papers, 2021 to 2025). A malignant, usually aggressive tumor composed of atypical, neoplastic melanocytes. "Knockdown of ANKRD6 was revealed to increase melanoma cell proliferation and migration." (PMID 34550275, 2021).
diabetes (1 paper, 2017). "In addition, WNT5A expression levels in VAT correlated with those of some of the PCP signaling components, such as VANGL2, PRICKLE1, DSH1,2,3 and DIVERSIN/ANKRD6 only in subjects with diabetes." (PMID 29229927, 2017). "Specifically, VAT expression of ROR2, FZD7, VANGL2 and PRICKLE1 correlated with that of DSH1,2,3 and DIVERSIN/ANKRD6 in the diabetes group, but not in most cases in the group without diabetes." (PMID 29229927, 2017).
vitiligo (1 paper, 2021). Generalized well circumscribed patches of leukoderma that are generally distributed over symmetric body locations and is due to autoimmune destruction of melanocytes. "As the results shown that the expression of ANKRD6, ATG13, SEMA4D, SMAD3, and PAXILLIN were all significantly downregulated in vitiligo." (PMID 33968138, 2021). "Furthermore, we detected the expression of target genes such ANKRD6, ATG13, SEMA4D, SMAD3, and PAXILLIN to verify that these circRNA-ceRNA networks are involved in the pathological process of vitiligo." (PMID 33968138, 2021).
tumor (6 papers, 2011 to 2024). "ANKRD6-silenced cells displayed a significant reduction in tumor growth with respect to control cells." (PMID 38480611, 2024). "Consistent with this, the tumor weight was significantly lower in those derived from ANKRD6-silenced cells." (PMID 38480611, 2024). "These genes are ANKRD6, ITIH3, SORCS3, NPY1R and CCDC178, which form a signature associated to adverse clinic-pathological features such as advanced tumor stage, poor prognosis and disease recurrence in GC." (PMID 38480611, 2024). "Noteworthy, overexpression of ANKRD6, ITIH3 and SORCS3 was detected in tumor compared with control tissue in the patients presenting poor survival." (PMID 38480611, 2024). "In relation to expression, we observed a progressive and significant increase of ANKRD6 and ITIH3 across the tumor stages." (PMID 38480611, 2024). "The HRs were less than 1 for CD27-AS1 and ANKRD6 and larger than 1 for miR-1275 in the DFS curve analysis, further indicating their tumor suppressor and oncogenic roles, respectively." (PMID 34550275, 2021). "Weak positive staining of ANKRD6 was also present in tumor tissue compared with the negative staining in normal tissue, also consistent with the survival data." (PMID 36226177, 2022).
cancer (4 papers, 2019 to 2024). A tumor composed of atypical neoplastic, often pleomorphic cells that invade other tissues. "Moreover, our results confirm that ANKRD6 is commonly overexpressed in cancer where it is associated to poor outcome and malignancy." (PMID 38480611, 2024). "In addition, the Ankyrin Repeat Domain 6 (ANKRD6), also known as Diversin, was highly expressed in several cancer tissues." (PMID 37310469, 2023). "Moreover, a number of target genes of miR-155 affect other cancer-related processes, such as cell growth and survival (CCND1 and GAB3), cell adhesion junction (ANKRD6 and SMAD2), proliferation (SOCS1 and STAT3), and apoptosis (TP53BP1)." (PMID 31744065, 2019). "Moreover, using the Cancer Cell Line Encyclopedia (CCLE), we determined that among our identified genes, in GC cells, ANKRD6 showed the highest levels on average, with the metastatic cell lines displaying higher expression than those cells derived from primary cases." (PMID 38480611, 2024).
ANKRD6 also shares sentences with these, for which no sentence is quoted: glioma (2 papers); gastric cancer (1); glioblastoma (1); metastatic disease (1); non-small cell lung carcinoma (1); thyroid carcinoma (1); viral infection (1).